TCF15 (transcription factor 15)
Description:
Early transcription factor that plays a key role in somitogenesis, paraxial mesoderm development and regulation of stem cell pluripotency. Essential for the mesenchymal to epithelial transition associated with somite formation. Required for somite morphogenesis, thereby regulating patterning of the axial skeleton and skeletal muscles. Required for proper localization of somite epithelium markers during the mesenchymal to epithelial transition. Also plays a key role in regulation of stem cell pluripotency. Promotes pluripotency exit of embryonic stem cells (ESCs) by priming ESCs for differentiation. Acts as a key regulator of self-renewal of hematopoietic stem cells (HSCs) by mediating HSCs quiescence and long-term self-renewal. Together with MEOX2, regulates transcription in heart endothelial cells to regulate fatty acid transport across heart endothelial cells. Acts by forming a heterodimer with another helix-loop-helix (bHLH) protein, such as TCF3/E12, that binds DNA on E-box motifs (5'-CANNTG-3') and activates transcription of target genes.
Synonyms: bHLHa40; EC2; PARAXIS
Tractability: No criterion of Open Targets' tractability assessment is met for any kind of drug.
Gene: Protein-coding gene on chromosome 20 (604,257 to 610,309, reverse strand). Ensembl gene ENSG00000125878.
Subcellular location: Nucleus
Subcellular location (Human Protein Atlas): Nuclear speckles
Gene Ontology:
Molecular function: DNA-binding transcription factor activity; DNA-binding transcription factor activity, RNA polymerase II-specific; E-box binding; RNA polymerase II transcription regulatory region sequence-specific DNA binding; bHLH transcription factor binding; DNA-binding transcription activator activity, RNA polymerase II-specific; protein dimerization activity; RNA polymerase II cis-regulatory region sequence-specific DNA binding
Biological process: developmental process; mesoderm development; negative regulation of hematopoietic stem cell differentiation; positive regulation of stem cell differentiation; positive regulation of transcription by RNA polymerase II; regulation of transcription by RNA polymerase II; stem cell population maintenance
Cellular component: nuclear speck; chromatin; nucleus; RNA polymerase II transcription regulator complex
Genetic constraint (gnomAD): Loss-of-function variants: 7 observed, 3.71 expected, observed/expected ratio (o/e) 1.89, 90% interval 0.92 to 1.96. That is too few expected variants to judge how well the gene tolerates losing a copy. Missense variants: 269 observed, 164.67 expected, observed/expected ratio (o/e) 1.63, 90% interval 1.48 to 1.81. Synonymous variants: 136 observed, 81.45 expected, observed/expected ratio (o/e) 1.67, 90% interval 1.45 to 1.9.
Homologues: Orthologues: chimpanzee TCF15 (97% identical), macaque TCF15 (97% identical), dog TCF15 (96% identical), pig TCF15 (95% identical), rat Tcf15 (92% identical), mouse Tcf15 (92% identical), rabbit TCF15 (88% identical), guinea pig TCF15 (84% identical), tropical clawed frog tcf15 (63% identical), zebrafish tcf15 (63% identical), Drosophila melanogaster CG33557 (32% identical), Drosophila melanogaster twi (22% identical), and 3 more. Paralogues in human: SCX (53% identical), MSC (28% identical), TCF21 (28% identical), HAND2 (25% identical), PTF1A (25% identical), TWIST1 (25% identical), HAND1 (24% identical), TWIST2 (24% identical), BHLHA9 (23% identical), TCF24 (22% identical), FIGLA (21% identical), TCF23 (20% identical), and 1 more.
Diseases named in the same sentence as TCF15 in open-access papers:
TCF15 is named in the same sentence as 9 diseases in open-access papers, as found by Europe PMC text mining. Sharing a sentence is not in itself a finding about the gene and the disease. The quoted sentences say what the papers report.
leukemia (3 papers, 2023 to 2025). A malignant (clonal) hematologic disorder, involving hematopoietic stem cells and characterized by the presence of primitive or atypical myeloid or lymphoid cells in the bone marrow and the blood. "The transcription factor 15 (TCF15), which is specifically expressed in leukemia stem cells, is responsible for the dysregulated expression of ALKBH5 in acute myeloid leukemia." (PMID 40986143, 2025). "DMRs were highly patient-specific, with only 89 genes containing DMRs in all three patients; however, this set included genes involved in leukemia, hematopoiesis, and multipotency, such as FLI1, EGFL7, and TCF15.36–40 We then analyzed the genomic features associated with DMRs across our cohort." (PMID 39553934, 2024).
heart failure (2 papers, 2015 to 2021). Inability of the heart to pump blood at an adequate rate to meet tissue metabolic requirements. "In our population study, we therefore also searched for association between the incidence of well-documented heart failure and variation in the MEOX2 and TCF15 genes." (PMID 26428460, 2015). "Since a reduced FA oxidation capacity causes energy starvation in a failing heart, modulating the technology of TEFA transport via several possible pathways, including PPARγ, Notch, and Meox2/TCF15, might open a new avenue to developing therapeutic strategies for energy-starved heart failure." (PMID 34940647, 2021). "Our experimental studies demonstrated that the MEOX2/TCF15 heterodimer facilitates the transport of fatty acids across cardiac endothelial cells and that in mice haplodeficiency in these genes results in impaired contractility of cardiomyocytes and heart failure." (PMID 26428460, 2015).
colon cancer (1 paper, 2021). "In the GCSC database, the methylation levels of FGF8, NOG, TCF15, TWIST1, TBX5, SIX2, and TIAM1 are higher in colon cancer." (PMID 34526059, 2021).
TCF15 also shares sentences with these, for which no sentence is quoted: acute myeloid leukemia (1 paper); cancer (1); diabetes (1); infection (1); Obesity (1); ovarian carcinoma (1).